CDC6 (cell division cycle 6)
Description:
Involved in the initiation of DNA replication. Also participates in checkpoint controls that ensure DNA replication is completed before mitosis is initiated.
Synonyms: HsCdc18; HsCDC6; CDC18L; MGORS5
Tractability: Small molecule: a structure with a bound ligand is known. PROTAC: UniProt records ubiquitination sites on it; ubiquitination databases record sites on it.
Gene: Protein-coding gene on chromosome 17 (40,287,831 to 40,304,657, forward strand). Ensembl gene ENSG00000094804.
Subcellular location: Nucleus; Cytoplasm
Subcellular location (Human Protein Atlas): Cytosol; Nucleoplasm; Cytokinetic bridge; Mitotic spindle
Pathways (Reactome):
DNA Replication: Activation of the pre-replicative complex; Assembly of the pre-replicative complex; CDC6 association with the ORC:origin complex; CDK-mediated phosphorylation and removal of Cdc6; Orc1 removal from chromatin
Cell Cycle: Activation of ATR in response to replication stress; G1/S-Specific Transcription; Transcription of E2F targets under negative control by DREAM complex
Gene Ontology:
Molecular function: protein binding; protein serine/threonine kinase binding; DNA replication origin binding; nucleotide binding; chromatin binding
Biological process: positive regulation of chromosome segregation; positive regulation of cytokinesis; regulation of mitotic metaphase/anaphase transition; DNA replication checkpoint signaling; DNA replication initiation; mitotic DNA replication checkpoint signaling; negative regulation of cell population proliferation; negative regulation of DNA replication; regulation of cyclin-dependent protein serine/threonine kinase activity; traversing start control point of mitotic cell cycle; cell division; cellular response to angiotensin; cellular response to vasopressin; positive regulation of fibroblast proliferation
Cellular component: nucleolus; nucleus; spindle midzone; spindle pole; cytoplasm; cytosol; nucleoplasm; spindle
Genetic constraint (gnomAD): Loss-of-function variants: 37 observed, 49.15 expected, observed/expected ratio (o/e) 0.75, 90% interval 0.58 to 0.99. The upper end of that interval is the gene's LOEUF score, 0.99, which puts it in group 4 of 6, group 1 being the genes least tolerant of losing a copy. Missense variants: 521 observed, 587.64 expected, observed/expected ratio (o/e) 0.89, 90% interval 0.82 to 0.95. Synonymous variants: 181 observed, 215.29 expected, observed/expected ratio (o/e) 0.84, 90% interval 0.74 to 0.95.
Gene-disease validity (ClinGen):
ClinGen rates the evidence that CDC6 causes each of these diseases.
Meier-Gorlin syndrome 5 (autosomal recessive): Limited.
Homologues: Orthologues: chimpanzee CDC6 (99% identical), macaque CDC6 (96% identical), rabbit CDC6 (88% identical), pig CDC6 (87% identical), dog CDC6 (86% identical), rat Cdc6 (80% identical), mouse Cdc6 (80% identical), guinea pig CDC6 (78% identical), tropical clawed frog cdc6 (64% identical), zebrafish cdc6 (49% identical), Drosophila melanogaster Cdc6 (36% identical), Caenorhabditis elegans cdc-6 (25% identical). Paralogues in human: ORC1 (27% identical).
Diseases named in the same sentence as CDC6 in open-access papers:
CDC6 is named in the same sentence as 113 diseases in open-access papers, as found by Europe PMC text mining. Sharing a sentence is not in itself a finding about the gene and the disease. The quoted sentences say what the papers report.
breast carcinoma (54 papers, 2008 to 2025). "Increased CDC6 expression is associated with poor survival and resistance to letrozole in the breast cancer patients." (PMID 36997866, 2023). "3′-UTR shortening of CDC6, a major regulator of DNA replication, is linked to higher CDC6 protein levels and increased S-phase entry in breast cancer cells." (PMID 33292571, 2020). "Both Cdc6 and Cdt1, when expressed in a high level, alone or in combination, were significantly associated with poorer survival in the breast cancer patient cohort (n = 1441)." (PMID 28428557, 2017). "In the present report, we found that expression of Cdc6 and Cdt1 was positively correlated with MCM2-7 overexpression, while high levels expression of Cdc6 and Cdt1 were associated with poor prognosis in breast cancer patients." (PMID 28428557, 2017). "Indeed, in the present study, we found that a high level expression of either Cdc6 or Cdt1 in the breast cancer specimens was associated with a shorter survival of the patients." (PMID 28428557, 2017). "In breast cancer and colon cancer, POLQ is associated with the upregulation of genome stability genes and replication initiation proteins such as CDC6, CDT1, and CDC45." (PMID 38270643, 2024). "Previous studies have indicated that CDC6 was upregulated in multiple types of cancer, including breast cancer, stomach cancer, glioma, and pancreatic cancer, which can facilitate the proliferation and invasion of cancer cells." (PMID 39376555, 2024). "CDC6 is overexpressed in several cancers, such as breast cancer, glioma, renal clear cell carcinoma, ovarian cancer, lung cancer, and chronic myeloid leukemia." (PMID 39684684, 2024). "We determined association of XBP1-gene signature (RRM2, CDC6 and TOP2A) with the outcome in breast cancer." (PMID 36997866, 2023). "As an example, the lncRNA-CDC6 can facilitate breast cancer progression by modulating the microRNA-215/CDC6 axis." (PMID 37934582, 2023). "CDC6 is overexpressed in various malignant tumors including ovarian cancer, pancreatic cancer, osteosarcoma and breast cancer, exerting an oncogenic effect." (PMID 37464398, 2023). "lncRNA-CDC6 elevates CDC6 expression by directly sponging miR-215 to function as a miRNA sponge, which boosts proliferation and metastasis in breast cancer-related cells." (PMID 37827696, 2023). "CDC6 plays an important role in DNA repair, and by stabilizing CDC6, estrogen ultimately enhances the DNA repair function in tumor cells, promoting the progression of breast cancer." (PMID 37627192, 2023). "Kong and Mahadevappa demonstrated experimentally that CDC6 plays an important role in the progression of breast cancer and can help predict the prognosis of breast cancer patients." (PMID 36077687, 2022). "For example, lncRNA CDC6 acts as a ceRNA to target CDC6 by sponging miR-215, thereby promoting breast cancer progression." (PMID 35420507, 2022). "Jasmonic acid induces biological activity in Arabidopsis and selectively inhibits breast cancer cell growth via CDC6 and mTOR." (PMID 36531013, 2022). "High levels of CDT1 and CDC6 are associated with poorer survival in the breast cancer patients, suggesting that CDT1 and CDC6 are potential therapeutic targets for treatment of breast cancer." (PMID 36359297, 2022). "For example, the level of lncRNA-CDC6 is elevated in breast cancer, and it promotes cell proliferation and migration through sponging of miR-215 and further regulating the expression of CDC6." (PMID 34789303, 2021). "CDC25A overexpression had been found in breast cancer and CDC6 overexpression in cervix, lung and brain cancer." (PMID 32817744, 2020). "In conclusion, our results indicate that expression of CCNB1 and CDC6 in breast cancer tissues is higher than in adjacent normal breast tissues." (PMID 31157164, 2019).
breast carcinoma (continued). "Our results suggest that Cdc6 is a potential prognostic marker and therapeutic target in breast cancer patients." (PMID 28428557, 2017). "We further tested the expression level of Cdc6 and Cdt1 in three breast cancer cell lines; three breast cell lines were chosen based on their aggressiveness and ER-positivity as well as their popularity in the literature." (PMID 28428557, 2017). "Further investigation is required to confirm the interaction between the expressions of CDC6 and MCMs in breast cancer." (PMID 28428557, 2017). "To confirm these in vitro findings, we investigated the impact of letrozole treatment on the expression levels of Cdc6 and Cdt1 in breast cancer." (PMID 28428557, 2017). "In short, our results elucidate the use of APA for CDC6 in response to E2 in breast cancer cells and will contribute to a more comprehensive understanding of E2 responsive gene expression changes in cancer cells." (PMID 22977174, 2012). "Clinical implication of CENP-F and CDC6 was examined for 253 archival breast cancers by the tissue microarray." (PMID 19102762, 2008). "Nuclear and cytoplasmic CDC6 expressions were positive in 23 (49%) and 16 (34%) of the 47 breast cancers and were detected simultaneously in 11 cases (23%)." (PMID 19102762, 2008). "The mRNA level of CDC6 was significantly higher in the high SUV group than the low SUV group of primary breast cancer (p = 0.025)." (PMID 19102762, 2008). "Similarly, lncRNA-CDC6 functions as ceRNA by sponging miR-251 to regulate the expression of CDC6, and thus it promotes proliferation in breast cancer cells and favors metastasis formation." (PMID 37143733, 2023). "The lncRNA-CDC6 could function as ceRNA via directly sponging of miR-215, and overexpression of the lncRNA-CDC6 further regulated CDC6 to promote the proliferation and metastasis of breast cancer cells." (PMID 37993951, 2023). "Furthermore, the expression of CDC6 is upregulated in multiple tumor types; CDC6 serves as a prognostic biomarker of breast carcinoma, colorectal cancer, pancreatic cancer, and other cancers." (PMID 35537781, 2022). "Finally, the increase in expression of the genes CCNE1, FANCI, RFC4, CDC6, and YWHAZ associated with poor prognosis in luminal A breast cancer (OS, HR:2.54, CI 1.69–3.82, log rank p = 3.6 × 10−6; RFS, HR:1.84, CI 1.53–2.22, log rank p = 6.5 × 10−11)." (PMID 33925616, 2021). "Our study utilized TCGA disease data and molecular target data through network pharmacology to demonstrate that Astragalus polysaccharide intervention in breast cancer may occur through regulation of CDC6 and CCNB1." (PMID 31157164, 2019). "CDC6, which is found in the COSMIC Gene Census database, is top-ranked for all TFBS’s and also for the CTCF double-hit mutations, with two mutations in breast cancer." (PMID 29354286, 2018). "Since assembly of the pre-RC requires the presence of Cdc6 and Cdt14, it is highly possible that overexpression of these two genes may also contribute to a poorer prognosis in breast cancer patients." (PMID 28428557, 2017). "Here, we investigated whether Cdc6, Cdt1 or Orc1 also confer prognostic value to breast cancer patients." (PMID 28428557, 2017). "And some of them, such as Cdc6 and Cdt1, are elevated by E2 treatment in breast cancer." (PMID 21040551, 2010). "For example, lncRNA BCRT1, MaTAR25, DSCAM-AS1, and CDC6 can promote breast cancer progression, BCRT4 can induce signaling transduction in breast cancer, LINC00673 can promote cell proliferation of breast cancer, and BORG can cause breast cancer metastasis and disease recurrence." (PMID 36744179, 2022).
breast carcinoma (continued). "As breast cancer with a high level expression of Cdc6 were less responsive to ER inhibition, it is tempting to speculate that the modality of combining inhibitions of ER and other pathways may be more beneficial to patients with high level of Cdc6, who respond less well to ER inhibition alone." (PMID 28428557, 2017). "However, little is known regarding the prognostic significance of Cdc6 and Cdt1 in breast cancer." (PMID 28428557, 2017). "Since Cdc6, Cdt1 and Orc1 work cooperatively with MCM2-7 to initiate DNA replication, we have investigated whether there are associations between the numbers of overexpressed MCM2-7 genes and expression of these three genes in breast cancer specimens." (PMID 28428557, 2017). "However, the roles of Cdc6 and Cdt1, which work with MCMs to regulate DNA replication, in breast cancers are largely unknown." (PMID 28428557, 2017). "Since Cdc6, Cdt1 and Orc1 work cooperatively with MCM2-7 to initiate DNA replication, in our current study we have investigated whether there are associations between these three genes and clinicopathological parameters or expression of MCMs in breast cancer." (PMID 28428557, 2017). "In order to prove the anti-tumor effect of Diazinon in BC, we used it to treat breast cancer cells and observed that it increased the expression of TAT while suppressing the expression of CDC6, RPA3, POLD1, and POLD2." (PMID 39334853, 2024). "We next analysed the expression of RRM2, CDC6 and TOP2A in two breast cancer patient datasets pre- and post-endocrine treatment (GSE10281, GSE80077)." (PMID 36997866, 2023). "We next determined the expression of RRM2, CDC6, and TOP2A mRNA and protein in XBP1-knockout sub-clones of MCF7 cells and ER-positive (MCF7, T47D, and BT474) breast cancer cells after treatment with STF083010." (PMID 36997866, 2023). "Our results showing the increased expression of RRM2, CDC6 and TOP2A in XBP1-dependent manner provides a mechanism for their overexpression in breast cancers." (PMID 36997866, 2023). "We showed that the post‐translational downregulation of CDC6, CDK2, Cyclin D1 and Cyclin D3 is part of the mechanism to reduce breast cancer cell viability." (PMID 33124043, 2021). "For example, genes involved in cell proliferation—such as CDC2, CDC6, and Thymidine kinase 1—are induced by E2 in MCF7 cells, whereas in the similar E2 responsive breast cancer cell line, 231ER+, these same genes are repressed." (PMID 33238524, 2020). "We went on to investigate the impact of inhibited ER signalling on the expression of Cdc6 and Cdt1 in the ER-positive MCF7 breast cancer cells and human breast cancer specimens." (PMID 28428557, 2017). "In unsupervised hierarchical clustering a distinctive group of male breast cancer with poor prognosis (p = 0.009; hazard ratio 3.4) was identified, characterized by frequent CCND1, MTDH, CDC6, ADAM9, TRAF4 and MYC copy number gain." (PMID 22527098, 2012). "In conclusion, copy number gain of the genes CCND1 (11q13), TRAF4 (17q11), CDC6 (17q21), and MTDH (8q22) is very common in male breast cancer (>40 %) and these genes probably play a role in male breast carcinogenesis." (PMID 22527098, 2012). "Gene copy number gain of CCND1, TRAF4, CDC6 and MTDH was seen in >40 % of the male breast cancer cases, with also frequent amplification." (PMID 22527098, 2012).
breast carcinoma (continued). "Here, by using an in silico and in vitro approach, we show that CDC6 is upregulated and its 3′-UTR is shortened in response to E2 in breast cancer cells." (PMID 22977174, 2012). "For example, CDC6 expression is markedly increased in breast cancer, particularly estrogen receptor (ER)-negative breast cancer." (PMID 39684684, 2024). "Further analysis demonstrated that the expression of cell cycle-related genes (CDC6, CDC25A, CDK1, ATM, E2F1, and MKI67) were much higher in breast cancer patients of 3 target genes high expression group or MIR3613 deletion group compared with their counterpart, respectively." (PMID 33494814, 2021). "More importantly, we also found that the prognostic significance of Cdc6 expression in the breast cancer patient cohort was independent of the prognostic significance of MCM2-7 genes." (PMID 28428557, 2017). "Importantly, breast cancer patients who responded to letrozole expressed significantly lower Cdc6 than those patients who did not respond." (PMID 28428557, 2017). "However, since Cdc6, Cdt1 and Orc1 all play an important role in DNA replication licensing, the reasons for Orc1 mRNA expression not being a prognostic factor in breast cancer may be worth further investigation." (PMID 28428557, 2017).